SLC6A14 (solute carrier family 6 member 14)
Diseases named in the same sentence as SLC6A14 in open-access papers (continued):
Sharing a sentence is not in itself a finding about the gene and the disease.
cystic fibrosis (7 papers, 2017 to 2022). Autosomal recessive disorder caused by pathogenic variants in the CFTR gene (cystic fibrosis transmembrane conductance regulator), which encodes a chloride and bicarbonate channel expressed in epithelial cells, and follow the diagnosis criteria. "SLC6A14 has been also proposed to modify the phenotype of cystic fibrosis – a fatal genetic disorder caused by mutations in the Cystic Fibrosis Transmembrane Conductance Regulator (CFTR) gene." (PMID 33195271, 2020). "A meta-analysis of large genome-wide association studies (GWAS) identified the SLC6A14 gene as a potential secondary modifier of cystic fibrosis comorbidities." (PMID 33302555, 2020). "Primarily described as involved in several cancer and colonic diseases physiopathological mechanisms, the SLC6A14 gene has been more recently identified as a genetic modifier of cystic fibrosis disease severity." (PMID 32166393, 2020).
prostate carcinoma (6 papers, 2016 to 2023). A carcinoma that arises from epithelial cells of the prostate gland. "Collectively, these results suggested that SLC6A14 overexpression is associated to better outcome for prostate cancer patients." (PMID 37397501, 2023). "An earlier study showed KRT80, RUNX, GATA6, SERPINB13, and SLC6a14 are important markers for prostate cancer progression, whereas we also identified KRT80, RUNX as well as GATA2, GATA2-AS1 in our study." (PMID 37476073, 2023). "Furthermore, authors revealed such genes for the TMPRSS2-ERG prostate cancer molecular subtype (B4GALNT4, ASRGL1, MYBPC1, RGS11, SLC6A14, GALNT13 and ST6GALNAC1)." (PMID 36077746, 2022). "Additionally, we revealed such genes for the TMPRSS2-ERG prostate cancer molecular subtype (B4GALNT4, ASRGL1, MYBPC1, RGS11, SLC6A14, GALNT13, and ST6GALNAC1)." (PMID 31447885, 2019).
metabolic syndrome (5 papers, 2021 to 2024). A cluster of metabolic risk factors for CARDIOVASCULAR DISEASES and TYPE 2 DIABETES MELLITUS. "As a blocker of SLC6A14, IDO1 and metabolic syndrome, α-MT can potentially have profound impact on several downstream signaling pathways such as mTOR and AhR because decreased amino acid entry into cells would impair mTOR signaling and decreased generation of kynurenine would suppress AhR signaling." (PMID 39902076, 2024).
breast tumors (4 papers, 2020 to 2025). "The expression of SLC6A14 was also induced by DEHP in a dose‐dependent manner in mouse breast tumors." (PMID 40959920, 2025). "Our initial analysis of SLC6A14 mRNA expression on human breast tumor samples available from The Cancer Genome Atlas database (TCGA) revealed a high variability in SLC6A14 transcript levels." (PMID 33400734, 2020). "In this study, we examined the potential of SLC6A14 as a therapeutic target in breast tumors." (PMID 33400734, 2020). "In particular, exploring the TCGA data, we show that SLC6A14 expression is highest in the basal-like subtype, which typically gives rise to the triple negative breast cancers (TNBC), the most aggressive type of breast tumors with no effective treatment strategies." (PMID 33400734, 2020).
Meconium ileus (4 papers, 2018 to 2022). Obstruction of the intestine due to abnormally thick meconium. "Based on GTEx data, the meconium ileus risk alleles are associated with decreased SLC26A9 expression, but increased ATP12A and SLC6A14 expression in the pancreas." (PMID 30807572, 2019). "Genome-wide association studies have identified SLC6A14, an electrogenic amino acid transporter, as a genetic modifier of CF-associated meconium ileus." (PMID 30004386, 2018). "The associated modifier loci colocalized with expression quantitative trait loci (eQTLs) for ATP12A (p = 3.35x10-8), SLC6A14 (p = 1.12x10-10) and SLC26A9 (p = 4.48x10-5) in the pancreas, even though meconium ileus manifests in the intestine." (PMID 30807572, 2019).
gastric cancer (3 papers, 2022 to 2024). A primary or metastatic malignant neoplasm involving the stomach. "Additionally, upregulation of SLC6A14 expression has been observed in gastric cancer, and depletion of SLC6A14 leads to the suppression of epithelial-mesenchymal transition-induced metastasis in gastric cancer through disruption of the PI3K/Akt/mTORC1 pathway." (PMID 38459595, 2024).
adenoma (1 paper, 2022). A neoplasm arising from the epithelium. "In the 482 cases, 302 CRC tissues showed higher SLC6A14 expression compared with the tissues from normal mucosa, adenoma, and liver cancer." (PMID 35907820, 2022).
breast invasive carcinoma (1 paper, 2023). "In breast invasive carcinoma no predictive value was observed by SLC6A14, SLC12A4 or SLC25A15 alone, but there was a nonsignificant trend for reduced survival in SLC6A14-high combined with SLC12A4-high or SLC25A15-high expression." (PMID 38066114, 2023).
colonic diseases (1 paper, 2020). "SLC6A14 expression has been shown to be differentially up-regulated in several pathological contexts, especially in cancer and colonic diseases." (PMID 32166393, 2020).
idiopathic pulmonary fibrosis (1 paper, 2020). Idiopathic pulmonary fibrosis (IPF) is a nonneoplastic pulmonary disease that is characterized by the formation of scar tissue within the lungs in the absence of any known cause. "Interestingly, a recent study using single RNA sequencing revealed that SLC6A14 expression was reduced in alveolar type II cells from idiopathic pulmonary fibrosis (IPF) patients compared to controls." (PMID 32166393, 2020). "SLC6A14 has been found to be downregulated in alveolar-type II cells of idiopathic pulmonary fibrosis (IPF) patients, while it is overexpressed in specimens from explanted lungs of patients with non-specific interstitial pneumonia compared to specimens from IPF patients." (PMID 32166393, 2020).
ischemia (1 paper, 2015). A hypoperfusion of the BLOOD through an organ or tissue caused by a PATHOLOGIC CONSTRICTION or obstruction of its BLOOD VESSELS, or an absence of BLOOD CIRCULATION. "Furthermore, statistical analysis revealed no significant decrease in the expression of SLC6A14 and DUOX2 in response to ischemia." (PMID 26222051, 2015).
liver cancer (1 paper, 2022). An epithelial or non-epithelial malignant neoplasm that arises from the liver. "Furthermore, we found that SLC6A14 expression was substantially increased in the CRC cell lines (HT29, HCT116, SW620 and Caco2) compared to the liver cancer cell line (Huh7)." (PMID 35907820, 2022).
metastatic tumors (1 paper, 2017). "SLC6A14 (solute carrier family 6, member 14) and TCN1 (transcobalamin 1) were down-regulated genes in primary and metastatic tumors." (PMID 28086829, 2017).
osteoporosis (1 paper, 2024). A condition of reduced bone mass, with decreased cortical thickness and a decrease in the number and size of the trabeculae of cancellous bone (but normal chemical composition), resulting in increased fracture incidence. "Five GMs, including GSTP1, TNF-α, TNF-β (LT-α), SLC6A14, and S1P, were associated with the musculoskeletal system and an increased risk of osteoporosis and reduced bone density." (PMID 40225935, 2024).
respiratory infection (1 paper, 2020). "However, some recent studies suggest that SLC6A14 may play an important role in the response to respiratory infection and fluid secretion related to CFTR." (PMID 32166393, 2020).
cancer (50 papers, 2014 to 2025). A tumor composed of atypical neoplastic, often pleomorphic cells that invade other tissues. "Depletion of SLC6A14 has been linked to amino acid starvation, suppressing epithelial-mesenchymal transition–induced metastasis in cancer." (PMID 39670859, 2025). "SLC6A14 has been implicated in oncogenesis owing to its role in regulating extracellular glutamine influx, a critical driver of cancer progression." (PMID 41444422, 2025). "SLC6A14 mediates amino acid uptake in multiple cell types where increased expression is associated with pathophysiological conditions including some cancers." (PMID 36291613, 2022). "Potentially, a subset of cancers with ER mutations leading to persistent ER activity driving SLC6A14 expression might be targeted or identified using this transporter." (PMID 28350329, 2017). "Several glutamine transporters have been confirmed to be widely upregulated in cancer and are associated with tumor invasion and metastasis, such as SLC1A5 (ASCT2), SLC7A5 (LAT1), and SLC6A14." (PMID 41040664, 2025). "DEHP enhances glutamine‐powered energy production via the transporter SLC6A14 and pushes mitochondria toward fusion, driving tumor initiation by boosting cancer stemness." (PMID 40959920, 2025). "In support of the contribution of SLC6A14‐mediated glutamine metabolism to cancer stemness, its downstream metabolite αKG rescued the sphere and organoid formation of MCF7 cells and PDO from the suppression by αMT." (PMID 40959920, 2025). "To investigate the metabolic changes induced by SLC6A14 in gemcitabine-resistant cancer cells, we analyzed metabolic enzyme levels, including those involved in the tricarboxylic acid (TCA) cycle, in the absence of SLC6A14." (PMID 41444422, 2025). "Transcriptomic analysis of the microdissected tumors (GSE164665) revealed higher expression of CXCR2, a known receptor for CXCL8, in stromal cells, whereas SLC6A14 was predominantly expressed in cancer cells." (PMID 41444422, 2025). "PD-L1 expression in cancer cells increased upon nutrient supplementation, whereas it was reduced following SLC6A14 silencing or glutamine deprivation." (PMID 41444422, 2025). "They found that SLC6A14 increases the uptake of glutamine, which fuels cancer cell growth and helps them evade the immune system." (PMID 41444422, 2025). "By blocking SLC6A14, they reduced cancer cell growth and improved immune response against the tumor." (PMID 41444422, 2025). "Among these DEGs, SLC6A14, a transporter responsible for mediating the influx of glutamine, serine, glycine, and methionine into cancer cells, displayed heightened expression in MVI." (PMID 39670859, 2025). "Aberrant SLC6A14 expression has been reported in multiple cancer types, where it promotes metabolic and signaling alterations." (PMID 41444422, 2025). "Cancer cells exhibit altered methyl group metabolism and upregulation of amino acid transporters such as SLC6A14, facilitating increased methionine uptake." (PMID 40427696, 2025). "High SLC6A14 expression correlates with cancer stemness signatures and earlier onset in patient cohorts." (PMID 40959920, 2025). "Previous research has underscored the potential of SLC6A14-targeted nanoparticles in resetting amino acid metabolism in cancer cells for enhanced anticancer therapy." (PMID 39670859, 2025). "Our results show that dual targeting of SLC6A14 with SLC25A15 or SLC12A4 is detrimental to cancer cell proliferation, especially in the context of low de novo serine synthesis." (PMID 38066114, 2023). "Notwithstanding the potential confounding factor of reduced proliferation, these results show that SLC6A14 transports a range of amino acids, with serine a dominant substrate in cancer cells." (PMID 38066114, 2023). "We further validated the potential of the three identified genes, S100P, BPIFB1, and SLC6A14, as biomarkers for predicting the recurrence of early-stage cancer." (PMID 37152984, 2023).
cancer (continued). "Of note, the correlation analysis between SLC6A14 and drug sensitivity in cancer cell lines revealed that SLC increases response to Erlotinib." (PMID 37397501, 2023). "SLC6A14 is a broad-spectrum amino acid transporter that is significantly up-regulated in PDAC as well as many cancer types." (PMID 35997090, 2022). "Recent studies show that the amino acid transporter SLC6A14 is upregulated in some cancers alongside glutamine metabolism." (PMID 35625849, 2022). "Mechanistically, we have shown that blockade of SLC6A14 essentially deprives the cancer cells of amino acids, which in turn inhibits mTORC1 signaling pathway, affecting overall protein translation." (PMID 35212370, 2022). "All these functions of SLC6A14 indicate that it deserves more attention as a new and effective method to target the anabolism of cancer cells." (PMID 35907820, 2022). "Due to its broad substrate selectivity, SLC6A14 is an ideal transporter to meet the increased needs for amino acids in cancer cells." (PMID 35907820, 2022). "Consistent with these functions, the amino acid transporters SLC7A5 and SLC6A14 are upregulated in tumors, making then potential targets for the pharmacological treatment of cancer (Kanai, 2022; Nałęcz, 2020)." (PMID 35229720, 2022). "Cancer cells accomplish this by selectively increasing expression of certain plasma membrane amino acid transporters including SLC6A14." (PMID 36291613, 2022). "The results showed that SLC6A14 expression was significantly higher in the cancer tissues than in the paired adjacent normal colon tissues." (PMID 35907820, 2022). "SLC6A14 is upregulated in many different cancer types, including colon cancer, cervical cancer, estrogen receptor-positive breast cancer, PCa, and osteosarcoma." (PMID 35625849, 2022). "Among these five amino acid transporters that have received attention with regard to their biological relevance to cancer, SLC6A14 and SLC38A5 stand out in terms of their functional features that are ideal for the promotion of cancer." (PMID 33806675, 2021). "Glutamine can also be transported by SLC6A14—a transporter catalyzing net amino acid uptake, which leads to an increased amino acid concentration in cancer cells." (PMID 34359969, 2021). "SLC6A14 is proposed to be upregulated in several cancers with the purpose of delivering amino acid nutrients into the cells, including colorectal cancer, cervical cancer, estrogen receptor positive breast cancer, and pancreatic cancer." (PMID 34867484, 2021). "Targeting proteins regulating SLC6A14 trafficking is proposed as an additional pharmacological treatment of cancer." (PMID 33195271, 2020). "Inhibition of heat shock proteins, known to be upregulated in cancer, directs SLC6A14 to degradation." (PMID 33195271, 2020). "A reduction of tumor growth was also observed in xenographs obtained with cancer cells, in which SLC6A14 was knocked-down." (PMID 33195271, 2020). "So SLC6A14 can be a target in cancer treatment, either by blocking the transporter with α-MT, what results in an arrest of cells at G1/G0 stage, amino acid deprivation and autophagy, or by affecting tumor-associated immune cells." (PMID 33195271, 2020). "In summary, expression data from human tumors and cancer cell lines show that SLC6A14 is overexpressed in a subset of tumors and suggest that, in these contexts, its preferential expression can be sufficient to fulfill tumor metabolic requirements." (PMID 33400734, 2020). "Use of commercial array of cDNA from squamous cell carcinoma patients and control normal tissues, as well as the fluorescence studies of cancer specimens demonstrated almost 6-fold upregulation of SLC6A14 at mRNA and protein level in cancer samples." (PMID 33195271, 2020). "Expression of SLC6A14 gene is significantly increased in several human cancer cell lines as well as in patients samples, in particular from solid tumors." (PMID 33195271, 2020).
cancer (continued). "In addition, SLC6A14 inhibition impaired sphere formation and reduced stemness-related gene expression, suggesting impaired cancer stemness." (PMID 41444422, 2025). "To investigate whether NF-kB interacts with PD-L1 in gemcitabine-resistant cancer cells, we assessed PD-L1 protein levels under SLC6A14 and NF-kB regulation." (PMID 41444422, 2025). "Since its selective overexpression in several tumors and its crucial role in cancer bioenergetic, SLC6A14 could represent a suitable therapeutic target, as well as a specific drug carrier." (PMID 37397501, 2023). "SLC6A14 has potential as a therapeutic target for both drug delivery and treatment of cancer, but also in other pathophysiological conditions associated with increased expression of this transporter such as the inflammatory bowel diseases ulcerative colitis and Crohn’s disease." (PMID 36291613, 2022). "Given that SLC6A14 plays a role in tumor progression and survival by promoting glutamine uptake into cancer cells, alloferon could be a potential adjuvant for the chemotherapeutic drug gemcitabine." (PMID 35625849, 2022). "Actually, the proliferation-promoting role of SLC6A14 has been stated in certain human cancers." (PMID 35865664, 2022). "SLC6A14 plays an important role in the uptake of glutamine and, therefore, in cancer cell survival." (PMID 35625849, 2022). "A pathophysiological role for SLC6A14 has been proposed in cancer." (PMID 36291613, 2022). "Pharmacological blockade of these nutrient transporters might offer a novel strategy in cancer therapy: “starve the tumor cells to death”, so a small-molecule inhibitor with minimal toxicity targeting SLC6A14 is worth seeking." (PMID 35907820, 2022). "Therefore, SLC6A14 has great potential for further investigation as a drug target for cancer treatment." (PMID 34867484, 2021). "In addition, SLC1A5 (ASCT2), SLC7A5 (LAT1), SLC7A11 (xCT), and SLC6A14 (ATB0+) have been shown to be positively expressed in cancer." (PMID 33937189, 2021). "Analysis of cancer patient survival correlated to SLC6A14 expression." (PMID 33195271, 2020). "Furthermore, SLC6A14 is one such cancer-specific amino acid transporter and is essential for tumor growth." (PMID 32190668, 2020). "Also 4 other miRNA were predicted to regulate SLC6A14 in cancer, their role, however, has to be investigated." (PMID 33195271, 2020). "Wnt signaling was reported to be involved in cancer progression, since SLC6A14 expression was shown to be reduced by silencing of β-catenin with shRNA and incubation of cancer cells with Wnt antagonist, while an opposite effect was observed after Wnt agonist treatment and β - catenin overexpression." (PMID 33195271, 2020). "Due to its unique properties, SLC6A14 emerges as a relevant target for cancer therapy." (PMID 33400734, 2020). "The microarray and RNAseq showed 15 SLC transporters being overexpressed when compared with the normal tissue; among them (apart from glucose transporter SLC2A1) lactate transporter SLC16A3 and SLC6A14, which was overexpressed at least 2-fold in cancer patients." (PMID 33195271, 2020). "For example, SLC1A5 takes up l-glutamine which is then exchanged for mTOR-activating l-leucine and other essential amino acids via the bidirectional antiporter SLC7A5, and both SLC1A5 and SLC7A5 are overexpressed in cancers along with glutamine transporter, SLC6A14." (PMID 28350329, 2017). "In silico analysis confirmed the SLC6A14 overexpression in these tumors when compared to both matched normal tissue and pooled GTEx control group, as well as in other epithelial cancers, suggesting a positive correlation between its expression levels and cancer development." (PMID 37397501, 2023). "In addition to playing an important nutritional support role in the development of cancer, SLC6A14 also effectively antagonizes toxins produced by a variety of infectious bacteria, and improves the reabsorption of Na + by intestinal cells, relieves diarrhea symptoms, and maintains homeostasis." (PMID 36419192, 2022).